KIF4A (kinesin family member 4A)
Diseases named in the same sentence as KIF4A in open-access papers (continued):
Sharing a sentence is not in itself a finding about the gene and the disease.
cancer (continued). "Recent evidence reveals that KIF4A’s functions extend beyond cell division, impacting a wide array of human diseases, particularly cancers." (PMID 41361459, 2025). "While KIF4A is best known for its oncogenic functions, recent studies demonstrate that its biological impact extends well beyond cancer." (PMID 41361459, 2025). "This connection presents KIF4A as a promising combined intervention target for patients with T2D complicated by cancer." (PMID 41361459, 2025). "Cancer cells often demonstrate a greater reliance on KIF4A for proliferation compared to normal cells, presenting a theoretical therapeutic window." (PMID 41361459, 2025). "The YAP/TEAD4 complex can inhibit apoptosis and promote cancer progression by activating kinesin family member 4A (KIF4A) expression." (PMID 38164167, 2024). "A biomarker study involving 165 BC patient samples analyzed the expression levels of four genes (CCNB1, KIF4A, TPX2, and TRIP13) and their association with clinical characteristics, revealing a correlation between elevated CCNB1 expression and cancer stage." (PMID 39795587, 2024). "Our research found that KIF4A affects cancer stem cells (CSCs) and promotes epithelial-to-mesenchymal transition (EMT), a process linked to cancer’s aggressiveness and spread." (PMID 38067227, 2023). "We also investigated the involvement of KIF4A in EMT, a process associated with increased invasiveness and metastatic potential of cancer cells." (PMID 38067227, 2023). "We analyzed the correlation between KIF4A expression and cancer progression, and TCGA molecular subtypes in the GEO dataset." (PMID 35126794, 2022). "If this is the case, then our data would demonstrate that there is a therapeutic window for inhibiting KIF4A as an anti-cancer strategy." (PMID 34326322, 2021). "KIF4A is critical to cancer progression and shows potential as a prognostic biomarker and therapeutic target." (PMID 33718157, 2021). "Previous studies have reported that KIF4A is involved in proliferation, apoptosis, and metastasis of cancer cells." (PMID 34775374, 2021). "Our clinical filtered screen results nominated KIF4A as a prostate-specific driver gene; however, DepMap CRISPR functional genomics data reported that KIF4A was essential in a number of cancer cell lines." (PMID 34326322, 2021). "Our interest in KIF4A was driven by the clinical data analysis showing this gene has many of the properties of a human cancer driver gene." (PMID 34326322, 2021). "The observed pan-cancer upregulation of KIF4A is probably an indicator of the increased mitotic rate in cancer cells." (PMID 34055488, 2021). "High expression of the KIF4A gene was significantly correlated with poor prognosis in four kinds of cancer, KIRC, KIRP, LUAD, and LIHC, as shown by Kaplan–Meier survival analysis." (PMID 34055488, 2021). "Many studies have noted the presence of upregulated expression of KIF4A in various cancer tissues and its positive correlation with poor prognosis." (PMID 34055488, 2021). "Elevated expression of the KIF4A protein was also verified in five types of cancer using immunohistochemistry data from the Human Protein Atlas (HPA)." (PMID 34055488, 2021). "KIF4A is essential to cancer progression and therefore has the potential to be a prognostic biomarker and therapeutic target." (PMID 30744636, 2019). "KIF4A is aberrantly expressed in a variety of cancers, and KIF4A is overexpressed in most tumors but also low-expressed in a few tumors, suggesting its distinct functions and mechanisms for different tumors." (PMID 31072351, 2019). "Previous studies have reported that KIF4A participates in regulating the proliferation and apoptosis of cancer cells." (PMID 29706624, 2018). "We identified that KIF4A expression was specifically detected in the nucleus of HCC cell from the cancer tissues in the vast majority of HCC samples (122/136 cases, 89.7%), while others presented negative expression (14/136 cases, 10.3%)." (PMID 29396392, 2018).
cancer (continued). "Kaplan-Meier analyses were used on the TCGA cohorts to assess the prognostic value of KIF4A expression among different human cancer types." (PMID 28646197, 2017). "We further evaluated the prognostic significance of KIF4A expression across human cancer types by utilizing The Cancer Genome Atlas (TCGA) database." (PMID 28646197, 2017). "We found that higher levels of KIF4A mRNA were correlated with shorter overall survival in other 9 human cancer types, which is consistent with studies performed by other researchers." (PMID 28646197, 2017). "Both KIF4A and its binding proteins such as PARP-1, BRCA2 and PRC1 have been implicated in multiple types of human cancers." (PMID 28160558, 2017). "Among the 186 curated KEGG gene sets, we found several cancers related pathways were significantly enriched in the high-KIF4A group." (PMID 28646197, 2017). "Therefore, we hypothesized that KIF4A might be associated with cancer progression." (PMID 24386490, 2013). "Collectively, these studies identify KIF4A as a pivotal oncogene with broad implications across different cancers, influencing malignant progression through its regulation of diverse biological processes such as the cell cycle, metabolism, apoptosis, EMT, and the immune microenvironment." (PMID 41361459, 2025). "Kinesin family member 4A (KIF4A) is upregulated in a variety of cancers." (PMID 37039264, 2023). "KIF4A regulates cell migration and invasion, which are important factors in cancer metastasis." (PMID 38067227, 2023). "UBC patients with high KIF4A expression had poor cancer‐specific survival and overall survival." (PMID 37039264, 2023). "In the pan-cancer analysis, KIF4A was upregulated in most tumors (21/33)." (PMID 35126794, 2022). "MiR‐379‐5p exhibited its cancer suppressive function by targeting KIF4A in BC cells." (PMID 35608059, 2022). "Firstly, we identified the expression of KIF4A in various cancers and focused on EC." (PMID 35126794, 2022). "KIF4A exhibited upregulated expression in eleven types of cancer." (PMID 34055488, 2021). "We will further use bioinformatics to analyze whether KIF4A is involved in chromosome segregation and whether it is abnormally expressed in various types of cancer." (PMID 34055488, 2021). "KIF4A was also found to be upregulated in multiple cancer types." (PMID 34055488, 2021). "Among the pan-cancer DEGs, KIF4A showed elevated expression in eleven types of cancer." (PMID 34055488, 2021). "Therefore, further studies are needed to obtain a deeper understanding of the complex roles of KIF4A in cancer development and progression." (PMID 30872592, 2019). "Due to its significant role in cancer development and progression, we wondered whether Skp2 expression was also related to KIF4A in this study." (PMID 29396392, 2018). "Functional assays, including a CCK-8 cell proliferation assay, colony formation analysis, cancer xenografts in nude mice, cell cycle and apoptosis analysis, indicated that KIF4A obviously enhanced cell proliferation by promoting cell cycle progression in vitro and in vivo." (PMID 29706624, 2018). "Along with our results on HCC, these findings strengthen the proposal that KIF4A may function as a general oncogene in multiple human cancer types." (PMID 28646197, 2017). "PHF14- or KIF4A-depletion alone notably impaired the proliferation of the cancer cells." (PMID 28160558, 2017). "In addition, the prognostic significance of KIF4A expression in other cancer types was validated in TCGA cohorts." (PMID 28646197, 2017). "KIF4A might hold a promise for the development of anticancer drugs and cancer vaccines as well as a prognostic biomarker in clinic." (PMID 24643254, 2014). "Moreover, therapeutic strategies that target KIF4A, especially combination therapies involving chemotherapy, targeted therapy, or immunotherapy, provide exciting new directions to address two significant challenges in cancer treatment: therapy resistance and immune evasion." (PMID 41361459, 2025).
cancer (continued). "KIF4A regulated the expression of the secretory factor plasminogen activator inhibitor-1 (PAI-1), demonstrating that it sustains cancer malignancy through an autocrine loop." (PMID 38067227, 2023). "Cancer growth can also be reliant on high expression of specific E2 cell cycle target genes including AURKA, KIF4A, STAG1, CTCF, and RPA1, all of which were identified highly expressed in at least one of the at-risk samples studied here." (PMID 35459280, 2022). "For the six cancer types (BRCA, KIRC, LUAD, LUSC, PRAD, and THCA) containing >50 normal samples, BUB1B, KIF4A, and MELK were among the 30 with the most significantly upregulated local entropy of four cancer types." (PMID 34097054, 2021). "The five genes (FANCB, KIF15, KIF4A, ERCC6L, and UBE2C) are all involved in fundamental cellular functions and found in many types of cancers." (PMID 32703154, 2020). "KIF4A, KIF14 and KIF20A are shown to be overexpressed across many human cancer types suggesting a link between expression levels and overall survival." (PMID 30991738, 2019). "Multiple kinesins are involved in the development of cancer, including KIF11 and KIF4A, which were down-regulated by both FAK inhibitors." (PMID 25277206, 2014). "Future research could explore the correlation between three kinesin genes (KIF4A, KIF20A, and KIF11) and cancer stem cells, potentially leading to new discovery.However, there were a few limitations in this study." (PMID 41462522, 2025). "For the first time, it integrates KIF4A’s functions in non-neoplastic conditions, moving beyond a cancer-centric perspective while thoroughly discussing its clinical translation prospects." (PMID 41361459, 2025). "In this study, we found that KIF4A could be used as a prognostic factor for LUAD, and its high expression would promote the proliferation and migration of cancer cells." (PMID 41462522, 2025). "Notably, we observed cross-regulation between KIF4A and PAI-1, suggesting the existence of an autoregulatory loop involving KIF4A and PAI-1 in maintaining cancer malignancy." (PMID 38067227, 2023). "Furthermore, the immunohistochemical staining results based on the HPA database revealed a significantly high positivity of the ZWINT, RRM2, NDC80, KIF4A, CEP55, CENPU, and CENPF genes in cancer tissues compared to adjacent normal tissues." (PMID 35028418, 2022). "Overexpression of KIF4A and KIF18B was observed in various cancers." (PMID 36499051, 2022). "KIF4A, as a hub gene, promoted the progression of LUAD and might represent a potential therapeutic target for molecular cancer therapy." (PMID 33398330, 2021). "It will be of great interest to recruit more patients with different cancer types to test whether PHF14 and KIF4A are co-overexpressed and co-activated in other cancer types." (PMID 28160558, 2017). "Epidemiological studies indicate that environmental exposures, such as chemical burns to the esophagus, may promote carcinogenesis by upregulating multiple cell cycle core genes, including KIF4A (e.g., TOP2A, CCNB1), providing a unique perspective on its role in cancer initiation." (PMID 41361459, 2025). "Despite, the molecular mechanisms behind its overexpression are not yet clarified, it is atypical cancer-testis antigens and scrupulous inhibition of KIF4A using molecular agents could be a promising therapeutic strategy against NSCLC." (PMID 32752229, 2020).
infection (4 papers, 2018 to 2025). The state of being infected such as from the introduction of a foreign agent such as serum, vaccine, antigenic substance or organism. "Using lentivirus-mediated infection, cells stably expressing ectopically central spindle protein KIF4A-mGFP were generated from cells already expressing endogenous mCherry-PRC1." (PMID 34580180, 2021). "KIF4A has previously been shown to improve the transport of HIV and adenovirus capsids early in infection." (PMID 35312737, 2022). "Interestingly, Kif4A has been suggested to contribute to transport of HIV Gap proteins, and Kif4-mediated microtubule stabilization enhanced early infection of HIV-1." (PMID 29782552, 2018).
metabolic disorders (1 paper, 2025). "The following section summarizes its roles in neurodevelopmental, immune-mediated, infectious, and metabolic disorders, underscoring its broad clinical relevance.In neurodevelopmental disorders, variants in the KIF4A gene are linked to a range of congenital genetic diseases." (PMID 41361459, 2025).
KIF4A also shares sentences with these, for which no sentence is quoted: lung adenocarcinoma (5 papers); COVID-19 (3); acute myeloid leukemia (2); metastatic prostate carcinoma (2); multiple myeloma (2); adenoma (1); Alzheimer disease (1); anaplastic oligodendroglioma (1); autism (1); Azoospermia (1); bacterial infection (1); brain tumor (1); breast invasive carcinoma (1); Cirrhosis (1); colitis (1); cRcc (1); Crohn disease (1); Fryns syndrome (1); gonadotroph adenomas (1); gynecological tumors (1); head and neck cancer (1); Hepatitis (1); Hydrocephalus (1); idiopathic inflammatory myopathies (1); idiopathic pulmonary fibrosis (1); invasive ductal carcinoma (1); laryngeal squamous cell carcinoma (1); lentivirus infection (1); lymph node metastasis (1); metastatic disease (1).
A further 11 diseases each share a sentence with KIF4A in 1 paper.